LINC02605 (long independently transcribed non-coding RNA 2605)
Synonyms: RP11-79H23.3; IL-7-AS; AC083837.1
Gene: Long non-coding RNA gene on chromosome 8 (78,835,307 to 78,840,525, forward strand). Ensembl gene ENSG00000261618.
Diseases named in the same sentence as LINC02605 in open-access papers:
LINC02605 is named in the same sentence as 1 disease in open-access papers, as found by Europe PMC text mining. Sharing a sentence is not in itself a finding about the gene and the disease. The quoted sentences say what the papers report.
virus infection (1 paper, 2021). "Among the differential expressed lncRNAs upon viral infection, LINC02605 is up-regulated manifestly and is a potential regulator in antiviral immune response." (PMID 34804040, 2021). "LINC02605 is mainly located in the nucleus upon viral infection." (PMID 34804040, 2021). "Therefore, LINC02605 is an induced lncRNA by viral infection and plays a positive feedback in antiviral immune response through modulating the nuclear translocation of IRF3." (PMID 34804040, 2021).